BRCA1 (BRCA1 DNA repair associated)
Diseases named in the same sentence as BRCA1 in open-access papers (continued):
Sharing a sentence is not in itself a finding about the gene and the disease.
breast cancer (continued). "“I do see that I have a little chance of getting breast cancer even though I’m a male, and it’s probably increased in males with BRCA1 compared to normal males, but that is a very low chance." (PMID 23638402, 2013). "Recent studies have revealed that BRCA1 and BRCA2 germline mutation-related breast cancers show frequent overexpression of hypoxia inducible factor-1α (HIF-1α), the key regulator of the hypoxia response." (PMID 23409121, 2013). "In the same vein, BRCA1 enhances sirtuin 1 activity, reducing cell growth and increasing apoptosis in breast cancer cells." (PMID 24127549, 2013). "Loss of BRCA1 with MYC overexpression leads to the development of breast cancer, especially, basal-like breast cancer." (PMID 23874497, 2013). "Human microarray data show that 24R,25(OH)2D3 modulate cell differentiation and proliferation, in particular by strongly influencing breast cancer 1, early onset (BRCA1) signaling pathway." (PMID 24116037, 2013). "QBS allows physicians to bedside recognize in quantitative way and precisely localize from birth both breast cancer IRR and the presence of BRCA-1 as well as BRCA-2 mutations." (PMID 23533376, 2013). "BRCA1 and BRCA2 are the most important genetic factors in hereditary breast cancer in the Han Chinese population, but the mutation rates are lower than in other ethnic groups." (PMID 23318652, 2013). "In particular, mitochondrial Brca1 proteins seem to have an antiproliferative activity on breast cancer cells." (PMID 24179442, 2013). "The names BRCA1 and BRCA2 stand for breast cancer susceptibility gene 1 and breast cancer susceptibility gene 2, respectively." (PMID 23401782, 2013). "In the United Kingdom, BRCA1 and BRCA2 mutations were identified in 5.9% of women diagnosed with breast cancer under the age of 36 years, and in 4.1% of women diagnosed with breast cancer between the age of 36 and 45 years." (PMID 22187038, 2012). "Noticeably, among the identified 44 datasets, several of them are related to proto-oncogene MYC and BRCA1, which are very well studied genes that play important roles in breast cancer pathogenesis." (PMID 23158478, 2012). "In this study, we have undertaken BRCA1 analysis in 308 individuals with TN breast cancer; the largest study to date." (PMID 22333603, 2012). "The cytoplasmic retention of Brca1 and Rad51 also correlates with activated Akt1 in sporadic breast cancer tissues." (PMID 22481935, 2012). "In breast cancer, TBX2 gene amplification is associated with invasive hereditary BRCA1- and BRCA2-related cancers, high-grade-sporadic breast tumors, and distant metastases." (PMID 22844464, 2012). "Germline mutations in BRCA1 and BRCA2 were analyzed by Sanger sequencing and multiple ligation-dependent probe amplification (MLPA) analysis in 431 women from the Malaysian Breast Cancer Genetic Study, including 110 women with TNBC." (PMID 23116406, 2012). "Several of the regions identified overlapped with loci and genes that have been previously implicated in breast cancer risk, including NBS1, BRCA1 and RAD51L1." (PMID 23190577, 2012). "Studies by the Consortium of Investigators of Modifiers of BRCA1/2 (CIMBA) have demonstrated that common alleles in RAD51, FGFR2, MAP3K1, TOX3/TNRC9, LSP1, SLC4A7/NEK10, a 2q35 locus and a 5p12 locus affect breast cancer risk in BRCA2 mutation carriers." (PMID 22513257, 2012). "Biopsies of sporadic breast cancer patients show strong correlation of Akt1 activation with cytoplasmic Brca1 and Rad51 localization." (PMID 22481935, 2012). "Within non-BRCA1/2 families, of a total of 19,137 males, 78 (0.4%) developed breast cancer with 32 cases available for use in the study." (PMID 23146383, 2012).
breast cancer (continued). "One group reported that a fraction of endogenous BRCA1 was exported from nucleus to cytoplasm within one hour of ionizing radiation-induced DNA damage in MCF-7 breast cancer cells." (PMID 24278741, 2012). "Only a single mouse (n = 13), doubly defective for Rbf and Brca1 activity (TgMFT121;TgWAP-Cre;Brca1f/f), developed mammary tumors at 386 days following Cre induction by multiple pregnancies." (PMID 23173005, 2012). "Inherited mutations in two genes, breast cancer 1 (BRCA1) and BRCA2, are associated with a particularly striking increase in breast cancer risk." (PMID 23284877, 2012). "Women carrying a deleterious BRCA1 or BRCA2 mutation not only face a strongly elevated lifetime risk for the development of breast and ovarian cancer but also for a second breast cancer." (PMID 23216834, 2012). "Further studies are needed to examine the contribution of HSF1 and BRCA1 depletion to the anticancer effects of WA in breast cancer." (PMID 25969759, 2012). "We showed earlier an inverse correlation between BRCA1-IRIS and BRCA1/p220 expressions in breast cancer cell lines." (PMID 22431556, 2012). "The majority of BRCA1-related tumors are basal-like breast cancers characterized by ER, PR and HER2 negativity while BRCA2-tumors resemble sporadic cases." (PMID 22405187, 2012). "Our results are concordant with a previous retrospective study on a cohort of 327 familial non-BRCA1/2 breast cancer cases." (PMID 23216834, 2012). "The genes BRCA1 and BRCA2 are associated with the risk of breast cancer, however these genes account for only 30-40% of the familial breast cancer cases, and only 3-4% of the total number of breast cancer cases." (PMID 22867275, 2012). "Throughout the continent of Africa, over a seventeen year period, 16 studies have evaluated 1150 patients for mutations in the BRCA1 and/or BRCA2 genes in breast cancer patients." (PMID 23519070, 2012). "For example, the hypermethylation of BRCA1 only occurs in 12% of ovarian cancers and 2% of breast cancers." (PMID 23034185, 2012). "Using MLPA, a novel deletion of BRCA1 exon 2 and a deletion of BRCA1 exon 8 were identified in two patients with breast/ovarian cancer and bilateral breast cancer, respectively." (PMID 23519070, 2012). "Based on gene expression arrays data, the molecular features of TN/BL breast cancers often overlap with those of BRCA1-assocaited tumors." (PMID 22511931, 2012). "There were 5 (1.2%) of 429 known BRCA1 mutation carriers and 35 (10.3%) of 339 BRCA2 carriers who developed breast cancer." (PMID 23146383, 2012). "The ectopic expression of BRCA1 in breast cancer is closely related to the happening, development and prognosis of young breast cancer patients." (PMID 23276146, 2012). "BRCA1 and BRCA2 mutant carriers impose a highly increased risk for hereditary or familial breast cancer." (PMID 22937096, 2012). "Collectively these data indicate that activation of AKT/mTOR pathway is involved in BRCA1-deficiency mediated tumorigenesis and that the inhibition of AKT/mTOR pathway can be used as a target for treatment of BRCA1-deficient breast cancers." (PMID 26097796, 2012). "These were likely laboratory contaminants, as the majority of them aligned to the breast cancer 1 and 2, early onset genes (BRCA1 and BRCA2), and targeted sequencing of these genes was conducted in the laboratory where the sequencing libraries were prepared." (PMID 22998755, 2012). "In male breast cancer, methylation was very rare in BRCA1, CDKN2A, VHL, ATM and CHFR (< 2%) - indicating that methylation of these genes does not seem to play a prominent role in male breast carcinogenesis." (PMID 22765268, 2012).
breast cancer (continued). "Quantitative PCR (qPCR) was performed to verify the expression of breast cancer-related genes (ERα, ErbB2, progesterone receptor (PR), and BRCA1) in each tumor cell lines." (PMID 23140372, 2012). "It is estimated that methylation of the BRCA1 promoter can be found in 11–14% of sporadic breast cancers." (PMID 22295252, 2012). "PUBMED and AJOL database were searched for publications addressing Breast Cancer and BRCA1 and BRCA2 genes." (PMID 23519070, 2012). "Although a spindle cell component (occasionally observed in human high-grade breast cancers) was occasionally observed in both tumors, this component was more prominent in BRCA1-IRIS-induced tumors." (PMID 22511931, 2012). "Cases (n=60) included 3 BRCA1 and 25 BRCA2 mutation carries, and 32 non-BRCA1/2 (BRCAX) carriers with strong family histories of breast cancer." (PMID 23146383, 2012). "We found that carcinogen-induced rat breast cancers overexpress rat BRCA1-IRIS mRNA in some aggressive primary tumors or upon disease progression." (PMID 22511931, 2012). "Well known breast cancer related proteins, like BRCA1, or related drugs, like tamoxifen, were included in these 500 pairs." (PMID 23134618, 2012). "The sample series includes four cases each of estrogen-receptor (ER)-positive, HER2-positive, and BRCA2-positive breast cancer; three cases of triple negative; and five cases of BRCA1-positive breast cancer." (PMID 22608083, 2012). "We have previously reported, in a small study of BRCA1-positive women with early breast cancer, that a high rate of complete pathologic response was achieved using cisplatin chemotherapy as a single agent in the neo-adjuvant setting." (PMID 22817698, 2012). "We performed a systematic review of English Language Literature to determine the role of BRCA1 and BRCA2 gene mutations in African breast cancer patients." (PMID 23519070, 2012). "BRCA1 and BRCA2 mutations were also identified in 15.4% for bilateral breast cancer and in 17.9% for multiple organ cancer, and BRCA2 mutations were identified in 25% for male breast cancer in one study." (PMID 22382806, 2012). "Using this approach, we were able to identify new gene functions in regulating cell mitosis in breast cancer by studying genes that have high correlation with the expression of the DNA repair protein, BRCA1." (PMID 22956898, 2012). "Aim of this work was to investigate the effects on human cell transcriptome of two missense variants, M1775R and A1789T, both located within the second BRCA1 BRCT domain and isolated from familial breast cancers." (PMID 22646717, 2012). "In fact, data from our own Inherited Cancer Registry (ICARE) at Moffitt indicated that of 253 female BRCA1 and BRCA2 mutation carriers, 127 had remaining at risk breast tissue (including 40 with a prior breast cancer diagnosis)." (PMID 26097796, 2012). "We applied GINI to a total of 24 LCLs, established from breast-cancer affected and unaffected women from three multiple-case non-BRCA1/2 breast cancer families." (PMID 22703186, 2012). "A published meta-analysis for BRCA1-related tumors reported a worse outcome among the breast cancer patients carrying a mutated BRCA gene, while BRCA1 mutated ovarian cancer patients had a more favorable clinical outcome." (PMID 22737296, 2012). "Germline mutations in the BRCA1 (MIM# 113705) and BRCA2 (MIM# 600185) genes confer a high lifetime risk of developing breast/ovarian cancer and account for about 16% of the breast cancer familial risk." (PMID 22632462, 2012).
breast cancer (continued). "We performed an immunohistochemical analysis of RAD21 expression in a cohort of 94 familial breast cancers (28 BRCA1, 27 BRCA2, and 39 BRCAX) and correlated these data with genotype and clinicopathologic parameters, including survival." (PMID 22537934, 2012). "We have shown that the spontaneous mammary tumors of our BRCA1 model can be transplanted orthotopically into syngeneic mice without loss of their genomic profile, morphology, or sensitivity to drug." (PMID 23028879, 2012). "The KRAS-variant was found in 22.7% (n = 5/22) of patients with two separate primary breast cancers and ovarian cancer; 0% (0/12) of BRCA1 patients, 33.3% (1/3) of BRCA2 patients and 57.1% (4/7) of uninformative patients." (PMID 22662244, 2012). "Pedigree analysis of clustered familial cases followed by positional cloning in the 1990s led to the discovery of tumor suppressor genes, BRCA1 and BRCA2, two major breast cancer susceptibility loci." (PMID 23107584, 2012). "Should they carry a pathogenic mutation in either the BRCA1 or BRCA2 gene, these patients do have a considerable long term risk for developing a second primary breast cancer (either ipsi- or contralateral) of up to 60%." (PMID 22569005, 2012). "The two high-penetrance genes most commonly mutated in HBOC are the tumor suppressor genes BRCA1 and BRCA2 (breast cancer, early onset 1 and 2)." (PMID 22655046, 2012). "Further studies are warranted to examine the contribution of HSF1 and BRCA1 depletion to the anticancer effects of WA in breast cancer." (PMID 25969759, 2012). "In this regard, it is also notable that cytoplasmic BRCA1 was found to suppress macroautophagy by reducing formation of autophagic vacuoles in breast cancer cells." (PMID 24278741, 2012). "PUBMED was searched using the following words in various combinations; ‘Breast Cancer’, ‘BRCA1’, ‘BRCA2’, ‘BRCA’, ‘Genes’, ‘Cancer Genes’, and ‘Africa’." (PMID 23519070, 2012). "This is significantly lower than for carriers of a pathogenic mutation in BRCA1 or BRCA2, who display a life-time risk for breast cancer of ~60–80%." (PMID 22672556, 2012). "HIF-1α overexpression is more frequent in BRCA1-related breast cancer compared to that in sporadic cancer in a small series of 30 cases." (PMID 22007214, 2012). "Top signalling pathways were “DNA double-strand break repair by homologous recombination”, “Role of BRCA1 in DNA damage response” and “Hereditary breast cancer signalling”." (PMID 22880105, 2012). "Hereditary breast cancer is associated with mutations in genes such as BRCA1 and BRCA2 and accounts for 5%–10% of all breast cancer." (PMID 23227345, 2012). "The relation of DNA methylation for BRCA1 and P16 with tumor recurrence has been reported with a high value in breast cancer patients." (PMID 22695536, 2012). "Cox proportional hazard analysis confirmed the trend that unaffected BRCA1 carriers were over one and a half times more likely to undergo BRRSO than breast-cancer affected-BRCA1 carriers (HR: 1.62; 95% CI: 1.01, 2.60)." (PMID 22187038, 2012). "An association has been described between the basal-like subtype and BRCA1-gene-related breast cancers." (PMID 22295242, 2012). "NMU-induced primary and invasive rat breast cancers expressed high levels of rat BRCA1-IRIS mRNA but low levels of rat ERα mRNA." (PMID 22511931, 2012). "Both BRCA1 and BRCA2 mutations have been found more often in patients with high grade breast cancer compared to age-matched control patients." (PMID 22736197, 2012). "BRCA1 (breast cancer tumor suppressor 1) is a RING finger-containing ubiquitin ligase of importance to breast cancer." (PMID 22876279, 2012).
breast cancer (continued). "Further recruitment of well characterised tumours in breast cancer families, in particular a focused collection of BRCA1 cases, is warranted to validate and characterise familial MBC further." (PMID 23146383, 2012). "In our further study, KIAA0101 was shown to be over-expressed in breast cancer cells, and interacting directly with the BRCA1 protein." (PMID 22956898, 2012). "In an attempt to identify additional high-risk genes involved in familial breast cancer, we have applied this disease-gene identification technique to affected and unaffected members of multiple- case non-BRCA1/2 breast cancer families." (PMID 22703186, 2012). "Methylation of the BRCA1 promoter occurs in 11–14% of sporadic breast cancers and in 5–31% of ovarian cancers and is often associated with LOH." (PMID 22347400, 2012). "Correlation of RAD21 expression with breast cancer-specific survival was further assessed for BRCA1, BRCA2, and BRCAX cancers." (PMID 22537934, 2012). "To confirm that, we silenced BRCA1/p220 for 24-168h in normal HME cells, MCF7 (estrogen receptor-positive, ER+) or MDAMB231 (ER−) breast cancer cell lines (both express detectable levels of BRCA1/p220 protein, left)." (PMID 22431556, 2012). "These investigations allowed us to evaluate the frequency of BRCA1/2-positive breast cancer cases at 2–5%." (PMID 22395474, 2012). "Although hereditary breast cancer is responsible for about 5–10% of all breast cancers, women carrying BRCA1 and BRCA2 gene mutations have especially high risk of breast cancer development." (PMID 22382806, 2012). "The most prevalent genes causing this pathology are BRCA1 and BRCA2 (breast cancer early onset 1 and 2), which also predispose to other cancers." (PMID 22655046, 2012). "In breast cancer cell lines with high level of Akt1 activity, IR-induced Brca1 and Rad51 foci formation and HRR are strongly impaired compared to cells with low Akt1 activity." (PMID 22481935, 2012). "This is the first description of a germline intragenic BRCA1 deletion in a breast cancer patient with a family history consistent with both LFL and HBC syndromes." (PMID 22691290, 2012). "In our study, BRCA1 protein is expressed in the cytoplasm of breast cancer cells of both of the young group and elderly group." (PMID 23276146, 2012). "Breast-ovarian cancer (BOC)-causing mutations and other genetic variants are distributed along the entire coding and non-coding regions of BRCA1 and BRCA2, and more than 3400 gene variants have been described in the Breast Cancer Information Core (BIC)." (PMID 23961350, 2012). "Nearly 3,500 different DNA variants of BRCA1 and BRCA2 have been reported at the Breast Cancer Information Core Database (BIC)." (PMID 22632462, 2012). "Further studies with larger population-based datasets are needed to determine the prevalence of BRCA1 and BRCA2 mutations and the cost-effectiveness of testing women diagnosed with isolated breast cancer, aged 40 to 49 years old." (PMID 23116406, 2012). "The identification of BRCA1 and BRCA2 mutations has dramatically changed the landscape of breast cancer in the past decade." (PMID 22290208, 2012). "This study is the first to explore the contribution of germline CNVs to BRCA1/2-negative familial and early-onset breast cancer." (PMID 22314128, 2012).